MIR1249 (microRNA 1249)
Synonyms: hsa-mir-1249; MIRN1249
Gene: MicroRNA gene on chromosome 22 (45,200,954 to 45,201,019, reverse strand). Ensembl gene ENSG00000221598.
Gene Ontology:
Biological process: miRNA-mediated post-transcriptional gene silencing
Cellular component: RISC complex
Diseases named in the same sentence as MIR1249 in open-access papers:
MIR1249 is named in the same sentence as 2 diseases in open-access papers, as found by Europe PMC text mining. Sharing a sentence is not in itself a finding about the gene and the disease. The quoted sentences say what the papers report.
tumor (1 paper, 2020). "Interestingly, when the cohort was split according to median MIR1249 tumor expression, cases with high expression were associated with worse prognosis independently of adjuvant chemotherapy." (PMID 31879968, 2020). "RNA‐seq data confirmed overexpression of MIR1249 in the tumor tissue in comparison to paired normal tissue in 55% of cases (The Cancer Genome Atlas [TCGA] cohort, n = 9)." (PMID 31879968, 2020). "At multivariate analysis (considering T stage, N stage, adjuvant chemotherapy and MIR1249 tumor expression), adjuvant treatment (hazard ratio [HR] 0.70; P < 0.001) and MIR1249 expression (HR 0.65; p: 0.004) maintained an independent prognostic value." (PMID 31879968, 2020). "When cohorts 1 and 2 were pooled together, 41% of cases showed increased MIR1249 expression in the tumor." (PMID 31879968, 2020). "Conversely, MIR1249 was overexpressed in the tumor compartment in comparison to paired nontumor tissue in 32% of cases." (PMID 31879968, 2020).
MIR1249 also shares sentences with these, for which no sentence is quoted: cancer (1 paper).